IDO1 (indoleamine 2,3-dioxygenase 1)
Diseases named in the same sentence as IDO1 in open-access papers (continued):
Sharing a sentence is not in itself a finding about the gene and the disease.
paracoccidioidomycosis (4 papers, 2017 to 2023). A systemic fungal infection caused by Paracoccidioides brasiliensis that is most often seen in immunocompromised patients. "In a previous study on pulmonary paracoccidioidomycosis, we demonstrated that the lack of IDO-1 expression caused an increased influx of activated Th17 cells to the lungs, with a simultaneous reduction in the number of Th1 and Treg cells." (PMID 36776848, 2023). "Indeed, in a pulmonary model of paracoccidioidomycosis, the absence of IDO1 expression led to a higher influx of activated inflammatory cells into the lungs, which promoted an increased expansion of T cells." (PMID 30186285, 2018).
pulmonary fibrosis (4 papers, 2021 to 2025). Chronic progressive interstitial lung disorder characterized by the replacement of the lung tissue by connective tissue, leading to progressive dyspnea, respiratory failure, or right heart failure. "To explore how IDO1 took part in the development of RILT, we conducted a correlation analysis between IDO1 and six common gene pathways involved in pulmonary fibrosis and inflammation based on the TCGA database." (PMID 36824664, 2023). "Thus, it appears that TDO2 is preferentially induced over IDO1 in pulmonary fibrosis in vivo." (PMID 39964756, 2025). "However, to our knowledge, the role of the other major kyn-producing enzyme, TDO2, has not been studied in the context of pulmonary inflammation or lung fibrosis, nor has it been shown to play a pathogenic role in the presence of the more ubiquitous IDO1 enzyme." (PMID 33491663, 2021). "Notably, the IDO1/AHR axis was recently shown to drive, at least in part, severe lung inflammation and pulmonary fibrosis following allogeneic stem cell transplant." (PMID 33491663, 2021).
sarcoidosis (4 papers, 2014 to 2024). Sarcoidosis is a multisystemic disorder of unknown cause characterized by the formation of immune granulomas in involved organs. "A previous study reported that patients with lung sarcoidosis have depressed serum tryptophan/kynurenine ratios, indicating an increased activity of IDO1." (PMID 36830609, 2023). "We identified weak expression of IDO1 in several sarcoidosis lesions along with bright expression of PD-L1, as observed by MIBI-TOF." (PMID 35058616, 2022). "However, the lymphadenopathy with the highest amount of interfollicular IDO1+ cells, which was also the only lymphadenopathy in which endothelial cells expressed IDO1, was in a patient with sarcoidosis." (PMID 36830609, 2023). "In addition to leukocytes expressing IDO1, we noted one patient with sarcoidosis where endothelial cells expressed IDO1." (PMID 36830609, 2023). "However, we noted that there were only three AD patients with the presence of follicular IDO1+ cells, of which two patients had sarcoidosis and one patient had autoimmune hepatitis." (PMID 36830609, 2023). "Thus, our observation with only one patient with the endothelial expression of IDO1 might be due to the patients’ sarcoidosis." (PMID 36830609, 2023).
skin cancer (4 papers, 2021 to 2025). "The skin tumor microenvironment contained potentially tumor-permissive myeloid cells producing regulatory (IDO1) and Th2-associated mediators (CCL13, CCL17, CCL22)." (PMID 33968070, 2021). "Our studies support a model where simultaneous GLI-STAT activation increases IDO1 levels in skin cancer cells, inhibiting human effector T cells by tryptophan degradation and enhanced kynurenine concentrations." (PMID 39962447, 2025). "The cancer biomarker IDO1 has been reported to increase the conversion of Trp to Kyn10–12, which implies that non-invasive sampling of the Trp/Kyn ratio from the skin surface is a promising skin cancer biomarker." (PMID 33436784, 2021). "Elevated expression of IDO1 correlated with active HH/GLI and JAK/STAT signaling in skin cancer patients supporting the clinical relevance of the mechanistic data presented." (PMID 39962447, 2025).
temporal lobe epilepsy (4 papers, 2014 to 2025). A localization-related (focal) form of epilepsy characterized by recurrent seizures that arise from foci within the temporal lobe, most commonly from its mesial aspect. "Our study provides evidence that IDO1 may be a new therapeutic target for the treatment of temporal lobe epilepsy." (PMID 33679331, 2021).
adenoma (3 papers, 2016 to 2020). A neoplasm arising from the epithelium. "Consistent with this idea, neoplastic IDO1+ Paneth cells were particularly abundant in early adenomas of ApcMin mice." (PMID 32444775, 2020). "Lysozyme+ and Lysozyme+ IDO1+ Paneth cells were found in ten adenomas (four from FAP patients) and six adenomas (three from FAP patients), respectively." (PMID 32444775, 2020). "The relative contribution of Paneth cells to Ido1 expression was assessed by IF staining of the six adenomas harboring IDO1+ Paneth cells." (PMID 32444775, 2020). "In particular, FAP adenomas showed a perinuclear signal for IDO1 in Paneth cells." (PMID 32444775, 2020). "Moreover, we stained 14 early adenomas (5 from FAP patients) for neoplastic Lysozyme+ IDO1+ Paneth cells." (PMID 32444775, 2020). "However, we identified a much higher percentage of IDO1+ Paneth cells in small and early ApcMin adenomas with almost 30% in the colon." (PMID 32444775, 2020). "Moreover, Stat1-Ido1 expression correlated with Lysozyme expression in human TCGA data and IDO1+ Paneth cells were present in adenomas of FAP patients, indicating that human CRC also contain neoplastic IDO1+ Paneth cells." (PMID 32444775, 2020).
bladder tumor (3 papers, 2017 to 2021). "Findings from our study provide compelling evidence for co-expression of multiple immune checkpoint genes including, PD-1, PD-L1, IDO1, TIGIT, TIM-3, TGFB1, LAG3, and others, that potentially contribute to compensatory immune evasion in bladder tumors." (PMID 31174611, 2019).
cerebral malaria (3 papers, 2014 to 2020). A sequestration of Plasmodium falciparum in the brain, which can cause coma and/or seizures. "A less commonly known product of the endothelium in cerebral malaria is indoleamine dioxygenase-1 (IDO-1), one of three intracellular enzymes that convert tryptophan into N-formylkynurenine." (PMID 25177551, 2014). "However, IDO-1 GKO mice are not protected against fatal cerebral malaria, although pharmacological inhibition of the production of deleterious metabolites through the kynurenine pathway does reduce mortality." (PMID 25177551, 2014).
emphysema (3 papers, 2020 to 2022). "We also identified IDO-1+ R2D2 population in lung explants from emphysema, interstitial lung disease patients." (PMID 31959883, 2020).
endotoxemia (3 papers, 2012 to 2023). "Excessive tryptophan metabolism to kynurenine by the rate-limiting enzyme endothelial indoleamine 2,3-dioxygenase 1 (IDO) controls arterial vessel relaxation and causes hypotension in murine endotoxemia." (PMID 23216784, 2012). "Repeated low doses of LPS caused a decrease in circulating EPCs and l-kyn supplementation, mimicking IDO1 activation, significantly increased EPC numbers under homeostatic conditions preventing EPC decline in low-grade endotoxemia." (PMID 37081894, 2023).
fatty liver (3 papers, 2022 to 2025). "By feeding Apoe−/−Ido1−/− mice with HFCD, we show that IDO1-dependent Trp metabolism plays a distinctive role in regulating vascular versus fatty liver disease." (PMID 35563591, 2022).
gynecologic cancers (3 papers, 2021 to 2023). "Compared to patients with non-gynecologic cancers, more patients with gynecologic cancers express high levels of IDO-1 (44 vs. 13%, p<0.001), LAG3 (35 vs. 21%, p=0.008) and IL10 (31 vs. 15%, p=0.002)." (PMID 36824739, 2023). "High levels of IDO1 and LAG3 suggest that clinical trials with IDO1 inhibitors or LAG3 inhibitors, respectively, may be warranted in gynecologic cancers." (PMID 36824739, 2023).
HCMV infection (3 papers, 2019 to 2021). "The identification of KYN allowed us to define a mechanistic connection between HIF1α, IDO1, and AhR during HCMV infection." (PMID 33758082, 2021). "After 24 h we performed FACS analyses and detected the expression of the IFN-γ inducible molecule IDO1 as well as the efficiency of the CMV infection." (PMID 30781494, 2019). "Here we show that an hCMV infection reduced IDO1 activity in IFN-γ activated cells which subsequently resulted in an inhibition of the IDO1-mediated antiparasitic effect against T. gondii." (PMID 30781494, 2019). "Our findings suggest that this observed reduction of IDO1 activity by HCMV infection could be due to a HIF1α-dependent host response to suppress HCMV replication." (PMID 33758082, 2021). "INFγ-induced IDO1 gene expression and activity are reduced by HCMV infection (27, –, 31)." (PMID 33758082, 2021). "In the absence of HIF1α, HCMV infection enhances IDO1 synthesis of KYN." (PMID 33758082, 2021).
kidney tumors (3 papers, 2011 to 2025). "Intriguingly, endothelial IDO1 expression in kidney tumors was reported to be associated with a better prognosis, while in most other tumor types, IDO1 expression is associated with a worse clinical outcome." (PMID 25691885, 2015).
latent infection (3 papers, 2012 to 2022). "Metabolic profiles indicate increased activity of indoleamine 2,3 dioxygenase 1 (IDO1), decreased phospholipase activity, increased abundance of adenosine metabolism products, as well as indicators of fibrotic lesions in active disease as compared to latent infection." (PMID 22844400, 2012).
lymphopenia (3 papers, 2022 to 2025). Reduction in the number of lymphocytes. "Another cause of lymphopenia may be a shortage of the essential amino acid tryptophan (Trp) resulting from increased activity of the enzyme indoleamine 2,3-dioxygenase 1 (IDO-1), which is overexpressed in tumour cells." (PMID 41274959, 2025).
mesenchymal tumors (3 papers, 2017 to 2022). "Interestingly, mesenchymal tumors tend to express higher levels of immune-suppressive markers, that are potentially targetable, including Ido-1." (PMID 36419183, 2022). "All three GABA related genes -- glutamate decarboxylase 1 (GAD1) and 2 (GAD2) and 4-aminobutyrate aminotransferase (ABAT) -- were lower in mesenchymal tumors, which in contrast showed higher IDO1 (indoleamine 2, 3-dioxygenase 1) and TDO2 (tryptophan 2, 3-diaxygenase)." (PMID 28245795, 2017).
serous ovarian cancer (3 papers, 2016 to 2025). "CAFs from high-grade serous ovarian cancer (HGSOC) patients exhibited increased IDO1, COX2, and PD-L1 expression upon interaction with activated T cells, along with elevated immunosuppressive cytokines." (PMID 41078340, 2025). "In the remainder of this article, we will hence specifically refer to IDO1 when discussing the elevated metabolism of Trp found in the high-grade serous ovarian cancer patients." (PMID 36765849, 2023). "IDO1 has also been identified as a marker for poor prognosis in serous ovarian cancer patients." (PMID 27470985, 2016). "Our findings demonstrate enhanced amino acid metabolism by IDO1/TDO and IL4I1 in high-grade serous ovarian cancer patients, with markedly elevated metabolite levels in patient ascites samples compared to patient and healthy donor plasma." (PMID 36765849, 2023). "Our data suggest a role for both IDO1 and IL4I1 in high-grade serous ovarian cancer and indicate that IL4I1 may be involved in progression of the disease through metabolism of Phe and Tyr." (PMID 36765849, 2023). "Moreover, the enzymes IDO1 and IL4I1 were identified as active players in high-grade serous ovarian cancer, and a correlation between IL4I1 metabolite levels and disease stage was revealed." (PMID 36765849, 2023).
Shock (3 papers, 2020 to 2024). The state in which profound and widespread reduction of effective tissue perfusion leads first to reversible, and then if prolonged, to irreversible cellular injury. "Not only kynurenine but also a newly described tryptophan-derived tricyclic hydroperoxide formed by IDO1 in the presence of H2O2 were described to cause vessel relaxation, and may contribute to the pathogenesis of septic shock." (PMID 33363543, 2020).
Sjögren’s syndrome (3 papers, 2020 to 2023). "Analysis of the peripheral blood with flow cytometry of Sjögren’s syndrome patients detected higher expression of IDO-1 in the patients’ dendritic cells as compared to the dendritic cells of healthy controls." (PMID 32604956, 2020). "Elevated IDO1 activity and increased regulatory T cells have been discovered and correlated with disease severity and interferon-positive signatures in patients with Sjogren’s syndrome." (PMID 35778590, 2022).
status epilepticus (3 papers, 2021 to 2022). Status epilepticus is defined as a continuous seizure lasting more than 30 min, or two or more seizures without full recovery of consciousness between any of them. "Also, IDO1 levels, the KYN/TRP ratio, and the levels of pro-inflammatory cytokines in the sera and hippocampi were increased in mice during the acute phase and chronic phase after status epilepticus (SE)." (PMID 33679331, 2021).
urothelial bladder cancer (3 papers, 2021 to 2025). "Elevated COX‐2 levels boost PGE2 synthesis and release by TAN in the TME, leading to the upregulation of indoleamine 2,3‐dioxygenase 1 (IDO‐1) in urothelial bladder cancer cells." (PMID 39973474, 2025). "TANs upregulate the expression of indoleamine 2,3-dioxygenase 1 (IDO1) in cancer cells by secreting PGE2 in patients with urothelial bladder cancer (UBC), thereby inhibiting CD8+ T cell function." (PMID 40342932, 2025). "Since IDO‐1 acts as a potent T‐cell inhibitor through metabolic restrictions, restoring its levels by pharmacologically targeting COX‐2 activity improves antitumor response and ICI efficacy in animal models of urothelial bladder carcinoma." (PMID 39973474, 2025).
uterine cancer (3 papers, 2020 to 2024). Primary or metastatic malignant neoplasm involving the uterine corpus and/or the cervix. "Multivariable analysis showed an independent association between high IDO1 and high PD-L1, high CXCL10, high STAT1, and between high IDO1 and ovarian and uterine cancers; tumors in men were significantly associated with lower IDO1 levels (all multivariable p values <0.05)." (PMID 38632994, 2024).
acute graft versus host disease (2 papers, 2020 to 2021). A syndrome of immunologically mediated tissue damage that may occur following an allogeneic transplant, usually affecting the skin, liver, and GI tract. "Host derived IL-6 and Indoleamine 2,3 Dioxygenase-1 (IDO-1) were shown to regulate the behavior patterns and inflammation in the CNS during acute GVHD." (PMID 34691059, 2021).
acute lymphoblastic leukemia (2 papers, 2014 to 2019). Leukemia with an acute onset, characterized by the presence of lymphoblasts in the bone marrow and the peripheral blood. "We also asked whether blast cells from acute lymphoblastic leukemia (ALL) of either B-cell or T-cell lineage would express IDO1 in either a constitutive and/or an inducible manner." (PMID 24903009, 2014).
acute promyelocytic leukemia (2 papers, 2014 to 2025). An aggressive form of acute myeloid leukemia (AML), characterized by arrest of leukocyte differentiation at the promyelocyte stage, due to a specific chromosomal translocation t(15;17) in myeloid cells. "We investigated IDO1 expression and function in 37 children with newly diagnosed AML other than acute promyelocytic leukemia." (PMID 24903009, 2014).
aspergillosis (2 papers, 2019 to 2022). Aspergillosis is an infection, growth, or allergic response caused by the Aspergillus fungus. "We found that polymorphisms affecting the expression and/or function of IDO1 associate with increased risk of aspergillosis in the two cohorts of patients." (PMID 31134053, 2019). "Together, these results suggest that impaired IDO1 function along with increased inflammatory response are risk factors for aspergillosis in HSCT patients similarly to what observed in CF patients." (PMID 31134053, 2019). "It is known that IDO1 is defective in CF patients and that it plays a role in aspergillosis in HSCT." (PMID 31134053, 2019). "Finally, IDO1 has been proposed to provide a protective effect against pathogen-driven inflammation in aspergillosis, though this is thought to be mediated through IDO1 expression in DCs." (PMID 35493480, 2022). "Similarly, IDO1 has gained attention for its ability to control inflammation, pathogen immunity and tolerance in transplant recipients eventually leading to prevention of graft-vs-host reaction and reduction of aspergillosis incidence rates." (PMID 31134053, 2019).
autoimmune hepatitis (2 papers, 2023 to 2025). Hepatitis caused by autoantibodies. "In a murine model of autoimmune hepatitis, hepatic IDO1 activation accelerates the Kyn pathway, which via AhR signaling attenuates Th17 differentiation, expands Tregs, and suppresses Akt phosphorylation, ultimately ameliorating liver injury." (PMID 40963608, 2025).
Autoimmune Thyroiditis (2 papers, 2021 to 2024). "In the scarce animal studies, the role of local IDO1 expression in the experimental autoimmune thyroiditis (EAT) model was investigated." (PMID 38514790, 2024). "It has been shown that the blockade of cytotoxic T lymphocyte-associated protein 4 (CTLA-4) exacerbated autoimmune thyroiditis in NOD-H2h4 mice and induced an expression of IDO1 in mouse thyroid glands and peripheral antigen-presenting cells." (PMID 38514790, 2024). "It has been demonstrated that CTLA-4 blockade exacerbated autoimmune thyroiditis in NOD-H2h4 mice and induced a strong expression of IDO1 in mouse thyroid glands and peripheral APCs." (PMID 34576041, 2021).
autoimmune uveitis (2 papers, 2019 to 2025). An autoimmune form of uveitis (disease). "We suggest that a local IDO1 deficiency might enhance the chance for an unwanted activation of immune responses to unique retinal proteins with a subsequent development of autoimmune uveitis in the presence of an intact cellular immune system." (PMID 30781494, 2019).
bacteremia (2 papers, 2023 to 2025). "Together, these results showed that IDO1 targeting could be a therapeutic strategy in hvKp-induced murine bacteremia." (PMID 40096073, 2025).
behavioral disorders (2 papers, 2016 to 2021). "The higher activity of IDO1 in response to immune challenge has been implicated in behavioral disorders." (PMID 27314674, 2016).
breast adenocarcinoma (2 papers, 2023 to 2025). "Similarly, in a pulmonary metastasis model in which orthotopically engrafted 4T1 breast adenocarcinoma cells metastasize spontaneously to the lungs, Ido1-/- (Ido1-nullyzygous) animals exhibited significantly delayed pulmonary tumor outgrowth relative to WT animals." (PMID 37182174, 2023).
cardiac hypertrophy (2 papers, 2024). "Finally, in myocardial diseases, the IDO1-KYN-AhR pathway exacerbates pathological myocardial hypertrophy by modulating GATA4." (PMID 38883986, 2024). "Conversely, the application of an IDO1 inhibitor improved myocardial hypertrophy and remodeling." (PMID 38883986, 2024). "Even more interestingly, the depletion of IDO1 or inhibition of kynurenine in murine models was found to prevent the progression of cardiac hypertrophy and may represent a potential treatment target." (PMID 38999939, 2024). "Through a series of in vivo and in vitro experiments, they demonstrated that knockout of IDO1 and down-regulating KYN could mitigate pathological myocardial hypertrophy by modulating the expression of GATA4 (GATA binding protein 4) via AhR regulation." (PMID 38883986, 2024).
cervical (2 papers, 2020 to 2023). "The elevated IDO1 expression in cervical tumorsphere cells was inhibited by the inactivation of Notch1 activity by the knockdown of Notch1 or the treatment of a γ-secretase inhibitor." (PMID 32545442, 2020).